HAT1 (histone acetyltransferase 1)
Description:
Histone acetyltransferase that plays a role in different biological processes including cell cycle progression, glucose metabolism, histone production or DNA damage repair. Coordinates histone production and acetylation via H4 promoter binding. Acetylates histone H4 at 'Lys-5' (H4K5ac) and 'Lys-12' (H4K12ac) and, to a lesser extent, histone H2A at 'Lys-5' (H2AK5ac). Drives H4 production by chromatin binding to support chromatin replication and acetylation. Since transcription of H4 genes is tightly coupled to S-phase, plays an important role in S-phase entry and progression. Promotes homologous recombination in DNA repair by facilitating histone turnover and incorporation of acetylated H3.3 at sites of double-strand breaks. In addition, acetylates other substrates such as chromatin-related proteins. Also acetylates RSAD2 which mediates the interaction of ubiquitin ligase UBE4A with RSAD2 leading to RSAD2 ubiquitination and subsequent degradation. In addition to protein acetyltransferase, can use different acyl-CoA substrates, such as 2-methylpropenoyl-CoA (methacryl-CoA), and is able to mediate histone methacrylation. (Microbial infection) Contributes to hepatitis B virus (HBV) replication by acetylating histone H4 at the sites of 'Lys-5' and 'Lys-12' on the covalently closed circular DNA (cccDNA) minichromosome leading to its accumulation within the host cell.
Synonyms: KAT1
Tractability: Small molecule: a structure with a bound ligand is known; it has a high-quality binding pocket. PROTAC: ubiquitination databases record sites on it; its protein half-life has been measured.
Target class: Enzyme; Transferase
Gene: Protein-coding gene on chromosome 2 (171,922,429 to 171,986,153, forward strand). Ensembl gene ENSG00000128708.
Subcellular location: Nucleus matrix (Isoform A); Mitochondrion; Cytoplasm (Isoform B); Nucleus; Nucleus matrix; Nucleus, nucleoplasm
Subcellular location (Human Protein Atlas): Nucleoplasm
Pathways (Reactome):
Chromatin organization: HATs acetylate histones
Gene Ontology:
Molecular function: histone H4K12 acetyltransferase activity; histone methacryltransferase activity; protein binding; protein-lysine-acetyltransferase activity; histone acetyltransferase activity; histone binding
Biological process: DNA replication-dependent chromatin assembly; chromosome organization; internal protein amino acid acetylation; chromatin organization; subtelomeric heterochromatin formation
Cellular component: chromatin; chromosome, telomeric region; cytoplasm; mitochondrion; nuclear matrix; nucleoplasm; nucleus; protein-containing complex; histone acetyltransferase complex
Genetic constraint (gnomAD): Loss-of-function variants: 1 observed, 3.08 expected, observed/expected ratio (o/e) 0.32, 90% interval 0.11 to 1.44. That is too few expected variants to judge how well the gene tolerates losing a copy. Missense variants: 21 observed, 18.11 expected, observed/expected ratio (o/e) 1.16, 90% interval 0.82 to 1.66. Synonymous variants: 1 observed, 4.06 expected, observed/expected ratio (o/e) 0.25, 90% interval 0.086 to 1.15.
Homologues: Orthologues: chimpanzee HAT1 (99% identical), macaque HAT1 (99% identical), dog HAT1 (98% identical), rabbit HAT1 (98% identical), pig HAT1 (97% identical), rat Hat1 (96% identical), mouse Hat1 (93% identical), guinea pig HAT1 (92% identical), tropical clawed frog hat1 (73% identical), zebrafish hat1 (68% identical), Drosophila melanogaster Hat1 (39% identical), Caenorhabditis elegans hat-1 (31% identical).
Diseases named in the same sentence as HAT1 in open-access papers:
HAT1 is named in the same sentence as 57 diseases in open-access papers, as found by Europe PMC text mining. Sharing a sentence is not in itself a finding about the gene and the disease. The quoted sentences say what the papers report.
pancreatic cancer (15 papers, 2019 to 2026). "KAT1/HAT1 is also overexpressed and causes an increase in PD-L1 expression to regulate cancer immunity in pancreatic cancer cell lines and mouse models." (PMID 38914477, 2024). "Despite evidence of the critical role of HAT1 in pancreatic cancer progression and gemcitabine resistance, the underlying mechanism remains elusive." (PMID 34564701, 2021). "First of all, we demonstrated that HAT1 was overexpressed in pancreatic cancer and linked with poor prognosis in PDAC patients." (PMID 30709380, 2019). "Moreover, HAT1 depletion caused a notable increase of gemcitabine sensitivity in gemcitabine-resistant pancreatic cancer cell lines." (PMID 34564701, 2021). "The recognition of HAT1 in the regulation of PD-L1 expression suggests that HAT1 might be employed as a new diagnostic and prognostic marker and as a predictive marker for pancreatic cancer therapy, especially in immune checkpoint blockade therapy." (PMID 30709380, 2019). "The recognition of HAT1 in regulating tumor cell proliferation and cancer immunity indicated that HAT1 might be employed as a new diagnostic and prognostic marker and a predictive marker for pancreatic cancer therapy, especially in immune checkpoint blockade therapy." (PMID 30709380, 2019). "Despite some studies reporting that HAT1 can promote chemotherapy resistance in pancreatic cancer and liver cancer, research on its functional roles in tumors is still very limited." (PMID 41271679, 2025). "In malignant tumors, including liver cancer, pancreatic cancer, and cholangiocarcinoma, the expression level of HAT1 was significantly elevated, which suggested that HAT1 was closely related to tumorigenesis." (PMID 39781339, 2025). "In pancreatic tumors, HAT1 has shown its ability for influencing tumor proliferation and immunity, as well as treatment resistance, supporting its potential role as a relevant diagnostic, prognostic and predictive marker for cancer therapy." (PMID 38785507, 2024). "Due to the regulatory role of HAT1 in the PVT1 expression, HAT1 can be considered one of the therapeutic targets for reducing the oncogenic effects of PVT1 on pancreatic cancer cells." (PMID 38559560, 2024). "Regarding other HATs, researchers discovered an increased expression of histone acetyltransferase 1 (HAT1) in pancreatic tumor tissue compared to healthy tissue, and high expression of HAT1 correlated with a worse prognosis." (PMID 37659057, 2023). "HAT1’s role as an oncogene is well known, and solid tumors, including esophageal, lung, liver, and pancreatic cancer, have been shown to overexpress the gene." (PMID 37538397, 2023). "The study also showed that HAT1 regulated the expression of PD-L1 at the transcriptional level in both in vitro and in vivo models and that HAT1 knockdown reduced pancreatic tumor cell proliferation." (PMID 37394580, 2023). "Based on this mechanism, tripolyphosphate (TPP)-siHAT1 nanoparticles have been developed to inhibit HAT1 expression and overcome gemcitabine resistance in pancreatic cancer cells." (PMID 35965522, 2022). "Collectively, these data suggest that the ability of HAT1 to induce PVT1 expression in pancreatic cancer cells requires BRD4." (PMID 34564701, 2021). "In pancreatic cancer, HAT1 was shown to function as an important regulator in cancer immunity through transcriptional upregulation of PD-L1 in tumor cells, indicating that HAT1 could be used as a novel diagnostic and prognostic marker in immune checkpoint blockade therapy." (PMID 34880761, 2021). "In this study, we found that HAT1 overexpression in pancreatic cancer cells promoted gemcitabine resistance and that HAT1 silencing restored sensitivity to the antitumor effects of gemcitabine." (PMID 34564701, 2021). "In conclusion, HAT1-targeted therapy can improve observably gemcitabine sensitivity of pancreatic cancer cells." (PMID 34564701, 2021).
pancreatic cancer (continued). "HAT1 is often upregulated in pancreatic cancer and promotes pancreatic cancer cell proliferation by regulating PD-L1 expression; however, the oncogenic role of HAT1 in pancreatic cancer remains poorly understood." (PMID 34564701, 2021). "CS-TPP-siHAT1 nanoparticles have proved effective in inhibiting HAT1 expression and augmenting the antitumor effects of gemcitabine in pancreatic cancer." (PMID 34564701, 2021). "More importantly, we found that HAT1 enhanced the expression of EZH2 in pancreatic cancer cells in this study." (PMID 34564701, 2021). "Here, we used a CS-TPP carrier to deliver siHAT1 and suppress HAT1 expression in pancreatic cancer cells." (PMID 34564701, 2021). "Although EZH2 protein levels were reduced after HAT1 silencing, treatment with the proteasome inhibitor MG132 restored EZH2 protein levels in HAT1-knockdown pancreatic cancer cells." (PMID 34564701, 2021). "In this study, we found histone acetyltransferase 1 (HAT1) enhanced the tolerance of pancreatic cancer cells to gemcitabine and HAT1-mediated resistance mechanisms were regulated by PVT1 and EZH2." (PMID 34564701, 2021). "To assess the ability of CS-TPP-siHAT1 to suppress HAT1 expression, we incubated pancreatic cancer cells with different concentrations of CS-TPP-siHAT1 and for different times." (PMID 34564701, 2021). "Furtherly, HAT1 silencing increased three pancreatic cancer cell lines sensitivity to gemcitabine; HAT1 overexpression had the opposite effect." (PMID 34564701, 2021). "Using in vitro and in vivo models, authors also demonstrated that knockdown of HAT1 reduced the proliferation of pancreatic tumor cells, and downregulated PD-L1 expression." (PMID 32760400, 2020). "Our results indicated that PD-L1 mRNA is positively correlated with HAT1 mRNA in pancreatic cancer patient specimens (Pearson’s product-moment correlation coefficient r = 0.47, p = 4.4e-11)." (PMID 30709380, 2019). "To date, the biological effect and clinical relevance of HAT1 in pancreatic cancer is poorly understood." (PMID 30709380, 2019). "First, we knocked down of Hat1 in the murine pancreatic cancer cell line Panc 02 and showed that reducing the Hat1 resulted in decreasing the Pd-l1." (PMID 30709380, 2019). "Taken together, our results demonstrate that aberrant expression of HAT1 promotes tumorigenesis by modulating the cancer cell growth and the immune response in pancreatic cancer." (PMID 30709380, 2019). "Our data indicated that the knockdown of HAT1 blocked pancreatic cancer tumor growth, but the overexpression of HAT1 promoted the tumor growth in vivo." (PMID 30709380, 2019). "Consistent with the previous results in human pancreatic cancer cells, the knockdown of Hat1 slowed down the cells proliferation of murine pancreatic cancer cells in vivo." (PMID 30709380, 2019). "To further investigate the relationship between PD-L1 and HAT1, we analyzed the mRNA levels of PD-L1 (CD274) and HAT1 in a subset of pancreatic cancer patients." (PMID 30709380, 2019). "To investigate the expression level of HAT1 in pancreatic cancer, we first analyzed HAT1 mRNA levels in pancreatic cancer and nontumor pancreatic tissues by using the GEPIA web tool." (PMID 30709380, 2019). "Since HAT1 was upregulated in PDAC and promoted cell proliferation in pancreatic cancer cells, the more biological role of HAT1 needs to be explored." (PMID 30709380, 2019). "Histone acetyltransferase 1(HAT1) is a classic type B histone acetyltransferase and the biological role of HAT1 in pancreatic cancer is unclear." (PMID 30709380, 2019). "We showed that HAT1 is overexpressed in pancreatic cancer specimens and highly correlated with poor prognosis in pancreatic cancer." (PMID 30709380, 2019). "Taken together, our findings indicate that HAT1 acts as a growth promoting protein in pancreatic cancer." (PMID 30709380, 2019). "In this study, we demonstrate that HAT1 is upregulated and highly correlated with poor prognosis in pancreatic cancer specimens." (PMID 30709380, 2019).
pancreatic cancer (continued). "Then, our data showed that HAT1 acted as a tumor growth promoting protein in pancreatic cancer cells." (PMID 30709380, 2019). "In addition, PD-L1 expression was positively correlated with HAT1 expression in pancreatic tumor tissues." (PMID 37394580, 2023). "As is well known, pancreatic cancer was easily tolerated by chemotherapy, while upregulated HAT1 might led to the results." (PMID 34564701, 2021). "Our findings suggest that HAT1-induced gemcitabine resistance in pancreatic cancer may be mediated by the PVT1/EZH2 complex." (PMID 34564701, 2021). "Moreover, HAT1 silencing in pancreatic cancer cells enhanced apoptosis in response to gemcitabine treatment." (PMID 34564701, 2021). "The expression of HAT1 also was upregulated obviously in pancreatic cancer cells compared to the normal cells, which might be the potential cause of gemcitabine resistance." (PMID 34564701, 2021). "HAT1 is a promising therapeutic target for pancreatic cancer." (PMID 34564701, 2021). "Finally, we show that CS-PTT-siHAT1 nanoparticles suppress HAT1 expression and augment the antitumor effects of gemcitabine in pancreatic cancer cells." (PMID 34564701, 2021). "Herein, we show that HAT1 knockdown in pancreatic cancer cells increases gemcitabine sensitivity and decreases PVT1/EZH2 complex levels, suggesting that HAT1 may represent a promising therapeutic target in pancreatic cancer." (PMID 34564701, 2021). "Collectively, the findings presented here suggest that HAT1 may be a valuable therapeutic target in pancreatic cancer." (PMID 34564701, 2021). "As an oncogene, HAT1 is overexpressed and related to poor prognosis in a variety of solid tumors, such as HCCs, nasopharyngeal carcinoma, and pancreatic cancer, and can be a therapeutic target." (PMID 34880761, 2021). "Besides, we have previously shown that HAT1 promoted PD-L1 expression in pancreatic cancer cells in a BRD4-dependent manner." (PMID 34564701, 2021). "We have previously shown that HAT1 was overexpressed in pancreatic cancer and that HAT1 silencing reduced the expression of PD-L1 on the surface of pancreatic cancer cells in a BRD4-dependent manner, improve the therapeutic efficacy of immune checkpoint blockade." (PMID 34564701, 2021). "Furthermore, it was shown that PD-L1 expression positively correlated with HAT1 expression in pancreatic tumor tissues." (PMID 32760400, 2020). "HAT1 regulated PD-L1 expression in human pancreatic cancer cells." (PMID 30709380, 2019). "Our findings suggest that ascorbate could suppress PD-L1 expression by influencing the HAT1 level in pancreatic cancer cells." (PMID 30709380, 2019). "Our data demonstrated that overexpressed HAT1 promoted pancreatic cancer growth in vivo." (PMID 30709380, 2019). "In summary, we proposed a new understanding of the specific role of HAT1 in pancreatic cancer." (PMID 30709380, 2019). "The knockdown of HAT1 decreased the proliferation of pancreatic cancer cells in vivo and in vitro." (PMID 30709380, 2019). "In this study, we sought to determine the specific role of HAT1 in pancreatic cancer." (PMID 30709380, 2019). "Furthermore, our results suggested that HAT1 promoted cell proliferation in pancreatic cancer cells." (PMID 30709380, 2019). "The aberrant expression of HAT1 participates in promoting tumor cell growth in pancreatic cancer." (PMID 30709380, 2019). "Our results further showed that HAT1 regulated PD-L1 expression in pancreatic cancer, and PD-L1 has been reported to promote tumor cell growth not only via immune effects but also through tumor cell-intrinsic signals, including the regulation of autophagy and the mTOR pathway." (PMID 30709380, 2019). "Thus, HAT1 promotes gemcitabine resistance in pancreatic cancer cells." (PMID 35965522, 2022).
pancreatic cancer (continued). "Thus, we explored the influence of abnormal HAT1 expression on the sensitivity of several commonly used drugs in pancreatic cancer cells, which showed the significantly reduced IC50 for gemcitabine when HAT1 was knocked down, while the sensitivity of other drugs was slightly reduced or unchanged." (PMID 34564701, 2021). "Furthermore, the PANC-1 cells infected with pTsin-EV or pTsin-Flag-HAT1 used to establish the control or HAT1-overexpressing pancreatic cancer stable cell lines, respectively, were injected subcutaneously into the right flank of nude mice for the xenograft assay." (PMID 30709380, 2019). "We observed a positive correlation between the protein levels of HAT1 and EZH2 in pancreatic cancer tissues (Spearman correlation coefficient r = 0.5899, P = 0.0005)." (PMID 34564701, 2021). "We have previously shown that aberrant expression of histone acetyltransferase 1 (HAT1) enhanced PD-L1 expression and promoted pancreatic cancer cell proliferation by modulating the function of BRD4." (PMID 34564701, 2021). "Our data strongly support that HAT1 upregulates PVT1 and promotes gemcitabine resistance in pancreatic cancer by enhancing BRD4 binding to the PVT1 promoter." (PMID 34564701, 2021). "Tissue microarray of pancreatic cancer (n = 31) was used to conduct IHC analysis and ascertain the relationship between HAT1 and EZH2 in pancreatic cancer." (PMID 34564701, 2021). "Strikingly, we showed that HAT1 transcriptionally regulated PD-L1, and this process was mainly mediated by BRD4 in pancreatic cancer." (PMID 30709380, 2019). "The clinical relevance of HAT1 was examined by the GEPIA web tool, Western blotting and immunohistochemistry of pancreatic cancer tissue microarray slides." (PMID 30709380, 2019). "Histone acetyltransferase 1 (HAT1) is another recently identified succinyl-transferase, which promotes glycolysis and thus tumorigenesis in, e.g., human hepatoma cells and pancreatic cancer cells by enhancing the enzymic activity of PGAM1 via K99 succinylation." (PMID 36605449, 2022). "We also found that the protein but not the mRNA levels of EZH2 were decreased after HAT1 silencing in pancreatic cancer cells." (PMID 34564701, 2021). "Moreover, the expression of HAT1 increased in GR-PANC-1, which further illustrated HAT1 promoted the gemcitabine resistance of pancreatic cancer cells." (PMID 34564701, 2021). "This study suggests that HAT1 regulates the sensitivity of pancreatic cancer to gemcitabine by regulating PVT1/EZH2 complex, highlighting the importance of HAT1 in the development of gemcitabine resistance in pancreatic cancer." (PMID 34564701, 2021). "Furthermore, analyses using the GEPIA tool and ENCORI Pan-Cancer Analysis Platform indicated a positive correlation between HAT1 and PVT1 expression levels, suggesting that HAT1 regulates PVT1 expression in pancreatic cancer cells." (PMID 34564701, 2021). "We found that the mRNA levels of HAT1 in pancreatic cancer tissues were higher than in nontumor pancreatic tissues." (PMID 30709380, 2019). "Although we provide strong evidence that HAT1 inhibition may suppress tumor growth, reverse drug resistance, and improve the prognosis of pancreatic cancer, there are currently no HAT1 small molecule inhibitors." (PMID 34564701, 2021). "To further determine the correlation between HAT1 and PD-L1 in pancreatic cancer specimens, we examined the expression of these two proteins by performing immunohistochemistry (IHC) on a tissue microarray (TMA) containing a cohort of pancreatic cancer samples (n = 41)." (PMID 30709380, 2019). "Co-immunoprecipitation assays revealed an interaction between HAT1 and EZH2 in pancreatic cancer cell lines, regardless of endogenous or exogenous expression." (PMID 34564701, 2021). "Given that HAT1 functioned as a negative prognostic biomarker in PDAC, we wanted to explore the specific role of HAT1 in pancreatic cancer." (PMID 30709380, 2019).